REN (renin)
Diseases named in the same sentence as REN in open-access papers (continued):
Sharing a sentence is not in itself a finding about the gene and the disease.
diabetic nephropathy (continued). "In this regard, vasopressin production is increased in diabetic kidney disease where it activates intra-renal renin–angiotensin–aldosterone system activation." (PMID 39768750, 2024). "The current treatment of diabetic nephropathy includes tight glycemic control and management of blood pressure, with a preference for renin–angiotensin system (RAS) inhibitors." (PMID 39335472, 2024). "Agents targeting the RAAS pathway, such as angiotensin-converting enzyme inhibitors, angiotensin II receptor blockers, and renin inhibitors, are effective in slowing the progression of diabetic nephropathy." (PMID 39335472, 2024). "Given the clear mechanism by which irbesartan treats diabetic nephropathy, primarily involving the regulation of the renin-angiotensin-aldosterone system (RAAS), our study focused on UC-MSCs." (PMID 39080783, 2024). "NFKBIA regulates the activity of NFκB, which plays a role in processes such as the accumulation of advanced glycation end products and activation of the renin–angiotensin system pathways, protein kinase C, and oxidative stress in diabetic nephropathy." (PMID 38674089, 2024). "Most of the current strategies to prevent the complications of diabetic nephropathy still focus on preventing hyperglycemia, the early diagnosis of kidney disease, and antihypertensive treatment to reduce renin-angiotensin system activity." (PMID 36588165, 2023). "Advanced glycation end products (AGEs), inflammatory factors, fibrosis, renin, blood lipids and reactive oxygen species are all critical contributors to the pathogenesis of diabetic nephropathy." (PMID 37723622, 2023). "published a study that combined renin–angiotensin system blockade and canagliflozin in patients with diabetic nephropathy." (PMID 38274236, 2023). "Renin and angiotensin system inhibitors (RAASi) and sodium-glucose cotransporter-2 inhibitors (SGLT2i) are recommended for patients with diabetic kidney disease (DKD) to reduce the progression to end-stage kidney disease; however, they are under-prescribed." (PMID 36352203, 2023). "The initial course of treatment for the clinical management of diabetic kidney disease (DKD) involves renin-angiotensinogen-aldosterone (RAAS) system lowering with angiotensin-converting enzyme inhibitors (ACEi) or angiotensin receptor blockers (ARBs)." (PMID 36733548, 2023). "It has been found that after a 6 months’ therapy with vitamin D to diabetic nephropathy patients, the urine albumin, renin and serum creatinine levels were reduced, leading to a noticeable improvement of GFR for these patients." (PMID 36984797, 2023). "Finerenone, a selective non-steroidal mineralocorticoid receptor antagonist, in combination with inhibitors of the renin angiotensin aldosterone system, has been shown to be effective in reducing albuminuria in patients with diabetic nephropathy." (PMID 35603210, 2022). "The current meta-analysis was carried out to assess the efficacy of direct renin inhibitors in preventing the progression of diabetic kidney disease." (PMID 36204481, 2022). "The intrarenal levels of renin as well as the upregulation of renin RNA in proximal are increased in the early phases of diabetic nephropathy." (PMID 36013381, 2022). "Clinical practice guidelines recommend prescribing renin–angiotensin aldosterone system inhibitors (RAASi) to prevent diabetic nephropathy at any stage." (PMID 35484505, 2022). "Two out of four studies assessed the impact of direct renin inhibitors on progression from microalbuminuria to macroalbuminuria including a total of 8,904 patients with diabetic kidney disease." (PMID 36204481, 2022). "Results of previous clinical trials suggested that glomerular hyperfiltration driven by the activation of SGLT2 and the renin-angiotensin-aldosterone system (RAAS) is the possible pathomechanism of diabetic nephropathy." (PMID 36046822, 2022).
diabetic nephropathy (continued). "Dysregulation of the renin-angiotensin-aldosterone system (RAAS) plays a vital role in the pathogenesis of diabetic nephropathy, including pathogenesis of both micro- and macrovascular complications." (PMID 34979961, 2022). "The cornerstone of therapy to prevent diabetic kidney disease (DKD) is the strict control of blood pressure with the renin–angiotensin–aldosterone system blockade and blood glucose levels." (PMID 33430860, 2021). "Overall, endothelin receptor antagonists, in combination with renin-angiotensin-aldosterone system inhibitors, effectively reduce albuminuria and prevent the progression of diabetic kidney disease." (PMID 34909290, 2021). "It is noteworthy to mention that expression levels of ACE2 were found to be unaltered by exposures to renin-angiotensin-aldosterone system inhibitors (RAASi) in diabetic kidney disease." (PMID 34360529, 2021). "The prevention of diabetic nephropathy adopts the therapeutic principles of strengthening blood glucose, controlling blood pressure, and blocking the renin-angiotensin system." (PMID 34493223, 2021). "Proper function of connexins has already been shown to be crucial for regulation of renal hemodynamics and renin secretion, and there is also growing evidence for connexins to play a role in pathologic conditions such as renal fibrosis or diabetic nephropathy." (PMID 34365513, 2021). "Intensive glucose regulation decreases the risk of diabetic nephropathy and also suppresses the renin–angiotensin system (RAS) and is a significant treatment target both for the prevention and management of diabetic nephropathy." (PMID 34441977, 2021). "Animal models of early diabetic nephropathy identically showed decreased plasma renin activity and increases in kidney renin." (PMID 34830315, 2021). "Recently, it has been reported that simultaneous neprilysin inhibition and renin-angiotensin system modulations prevented diabetic nephropathy and our results confirmed the same." (PMID 32596035, 2020). "In phase II and III studies, esaxerenone plus a renin–angiotensin system inhibitor markedly reduced the urinary albumin-to-creatinine ratio (UACR) in hypertensive patients with diabetic nephropathy." (PMID 32616846, 2020). "The purpose of this systematic review was to investigate the scientific evidence to support the use of direct renin inhibitors (DRIs) in diabetic nephropathy (DN)." (PMID 32231590, 2020). "Until recently, the main treatment of diabetic kidney disease was with renin–angiotensin–aldosterone system inhibitors, and cardiovascular risk was mitigated primarily with statins and aspirin." (PMID 31337395, 2019). "Renin-angiotensin system blockers used in the treatment diabetic nephropathy include angiotensin converting enzyme inhibitors (ACEIs) and angiotensin II receptor 1 blockers (ARBs)." (PMID 30591810, 2019). "Hyperfiltration induces activation of tubuloglomerular feedback and the renin-angiotensin-aldosterone system, and these mechanisms play an important role in the progression of diabetic nephropathy." (PMID 31781668, 2019). "Diabetic kidney disease (DKD) is currently a leading cause of end-stage renal failure, while treatments with renin–angiotensin–aldosterone system blockers with normalization of hyperglycemia are regarded as the gold standard." (PMID 31546603, 2019). "Conventionally, it is accepted that renal hemodynamics changes, oxidative stress, inflammatory response, hypoxia and renin-angiotensin-aldosterone system (RAAS) are majorly responsible for the pathogenesis of diabetic kidney disease." (PMID 31390847, 2019). "Renin-angiotensin system blockade is an approved therapy for the management of diabetic nephropathy." (PMID 30591810, 2019). "Renal dysfunction is associated with the activation of the renin-angiotensin system (RAAS), evidenced by the elevation of angiotensinogen (Ang) in CKD and the increased release of renin in diabetic nephropathy." (PMID 30314359, 2018).
diabetic nephropathy (continued). "The blood pressure was increased as the diabetic nephropathy was present due to the activation of renin-angiotensin aldosterone system (RAAS) and inflammation in glomerulus." (PMID 30123184, 2018). "Intrarenal renin-angiotensin system (RAS) plays a crucial role in development of diabetic nephropathy (DN), which is the major renal complication of diabetes mellitus as well as the main cause of end-stage renal disease." (PMID 29053707, 2017). "Further, the plasma of individuals with diabetic nephropathy showed increased levels of acid activated renin." (PMID 26753721, 2016). "Among them, the renin-angiotensin system (RAS) is known as an important factor in the development of diabetic nephropathy." (PMID 27802313, 2016). "Current standard of care for diabetic nephropathy embraces stringent blood pressure control via blockade of the renin-angiotensin-aldosterone system and glycemia control." (PMID 27303648, 2016). "We tested minocycline as an anti-proteinuric adjunct to renin-angiotensin-aldosterone system inhibitors (RAASi) in diabetic nephropathy (DN) and measured urinary biomarkers to evaluate minocycline’s biological effects." (PMID 27019421, 2016). "Blocking the renin-angiotensin system is especially effective in protecting against diabetic nephropathy progression." (PMID 25965806, 2015). "The aim of this review is to explain the advances in newer agents to treat diabetic kidney disease, along with the background of the renin-angiotensin system blockade." (PMID 25945357, 2015). "Advanced glycation end products (AGE)-receptor for AGE (RAGE) axis and renin-angiotensin system (RAS) play a role in diabetic nephropathy (DN)." (PMID 25143788, 2014). "More recent studies suggests that the effect of vitamin D receptor activation is partly that of negatively regulating renin-angiotensin system, which plays a significant role in the development of diabetic kidney disease." (PMID 28197449, 2014). "It seems that treatment with vitamin D reduced the urinary urine albumin/creatinine ratio level by suppressing the compensatory renin increase in diabetic nephropathy." (PMID 28197449, 2014). "This patient had all clinical criteria for diabetic nephropathy, and proteinuria remitted after tight control of blood pressure with intensive inhibition of renin angiotensin axis." (PMID 23320147, 2012). "The renin inhibitor provides a promising alternative approach for the treatment of patients with chronic proteinuric non-diabetic kidney disease." (PMID 23326865, 2012). "For example, patients with more pronounced volume overload, stronger activation of the renin–angiotensin–aldosterone system, or those with specific comorbidities (e.g., diabetic nephropathy or HF) might derive a greater antihypertensive benefit." (PMID 41203854, 2026). "The renin‐angiotensin system (RAS) plays a pivotal role in the pathophysiology of diabetic nephropathy, and clinical trials such as IDNT and RENAAL have established the benefits of ARBs in slowing renal disease progression independent of blood pressure control." (PMID 40474699, 2025). "This phenomenon could be attributed to the hyalinization of the afferent arteriole and juxtaglomerular cells in individuals with diabetic nephropathy, leading to a decrease in renin secretion." (PMID 40106408, 2025). "Symptomatic treatment regimens, including intensive glycemic control, cholesterol level management, and renin-angiotensin system blockade for blood pressure regulation, are commonly administered in clinical settings to slow the progression of diabetic kidney disease (DKD)." (PMID 39139646, 2024). "Until recently, the renin–angiotensin–aldosterone system blockade, with angiotensin-converting-enzyme inhibitors (ACEis) and angiotensin receptor blockers (ARBs), was the sole treatment option for diabetic kidney disease (DKD)." (PMID 39274317, 2024).
diabetic nephropathy (continued). "In this study we investigated the effect of GLP-1R agonist liraglutide on blood pressure, hydration status, natriuresis and the activity of the renin–angiotensin–aldosterone axis in patients with diabetic kidney disease after a dose of liraglutide compared to placebo." (PMID 38424466, 2024). "In this paper we focused on the effect of a single dose of liraglutide and placebo on 24 h blood pressure profile, hydration, natriuresis and plasma concentration of renin, aldosterone and atrial natriuretic peptide in patients with diabetic kidney disease and impaired kidney excretory function." (PMID 38424466, 2024). "However, the vast majority of studies have demonstrated that renin-angiotensin system inhibitors in conjunction with integrative therapy are effective for treating diabetic nephropathy." (PMID 36733548, 2023). "Diabetic nephropathy used to be responsible for nephrotic range albuminuria, but recent studies reported lower rates of albuminuria, an observation partly explained by the broader prescription of blockers of the renin‐angiotensin system to delay progression." (PMID 35488507, 2022). "In a phase II clinical trial in patients with moderate to advanced diabetic nephropathy receiving renin–angiotensin system blockade (mean eGFR 35.5 mL/min/m2; mean UPCR 3.3 g/gCr), the participants were scheduled to receive a placebo or 2, 10, or 50 mg of LY2382770 monthly dosing for 12 months." (PMID 36558936, 2022). "Thus, the current meta-analysis was carried out to assess the efficacy of direct renin inhibitors in the prevention of the progression of diabetic kidney disease." (PMID 36204481, 2022). "Clinical practice guidelines recommend prescribing angiotensin converting enzyme (ACE) inhibitors and angiotensin receptor blockers (ARBs) which are the two major classes of renin–angiotensin aldosterone system inhibitors (RAASi) to prevent and manage diabetic nephropathy at any stage." (PMID 35484505, 2022). "Since beta cells are the key cells leading to T2D, we search for hub genes in CCSN of beta cells and find that ATP6AP2 is essential for regulation and storage of insulin, and the renin-angiotensin system involving ATP6AP2 is related to most pathological processes leading to diabetic nephropathy." (PMID 35885938, 2022). "Renin-angiotensin-aldosterone system plays important roles in the development of diabetic nephropathy (DN), and angiotensin converting enzyme (ACE) is the key factor in the process from angiotensin I to angiotensin II, but the variation and roles of serum ACE in DN patients are still unclear." (PMID 36992775, 2022). "Although hyperglycemia, oxidative stress and renin–angiotensin–aldosterone system (RAAS) activation promote renal damage in diabetic nephropathy, substantial evidence suggests that inflammation is a major trigger for the development and progression of diabetic nephropathy." (PMID 35057768, 2022). "Kininogen-1 plays a role in the kallikrein-kinin system (cooperating with the renin-angiotensin system); it has been suggested as a possible urinary biomarker for diabetic nephropathy and may effect renal protection." (PMID 34248840, 2021). "It is possible that the vasoprotective branch of the renin–angiotensin system might play a more pronounced role during volume-expanded hypertensive states and diabetic nephropathy." (PMID 33524393, 2021). "Diabetic nephropathy is also characterized by activation of the renin–angiotensin system (RAS)." (PMID 34199409, 2021). "Aliskiren is a direct renin inhibitor that it protects against diabetic kidney disease." (PMID 34577791, 2021). "In addition, numerous studies have demonstrated that the intrarenal renin–angiotensin system plays an important role in diabetic nephropathy." (PMID 32977573, 2020).
diabetic nephropathy (continued). "A similar effect on proteinuria was found with the MMPs-I BB-94 in an experimental model of kidney allograft rejection in mice and the tetracycline antibiotic doxycycline in human patients with diabetic nephropathy already under renin-angiotensin-aldosterone inhibition." (PMID 31963569, 2020). "Thus, the traditional use of renin–angiotensin–aldosterone system (RAAS) blockers alone is insufficient for preventing the progression of diabetic kidney disease in a large subset of patients." (PMID 32722394, 2020). "Moreover, the renin-angiotensin system along with growth factors and cytokines have also been shown to contribute to the onset and progression of diabetic kidney disease; however, the role of lipids in this context is poorly characterized." (PMID 32581831, 2020). "Clinical Studies with DRI in diabetic nephropathy that determined plasma renin activity." (PMID 32231590, 2020). "Preclinical studies with DRI in diabetic nephropathy that determined plasma renin or renal RAS." (PMID 32231590, 2020). "Furthermore, when combined with renin-angiotensin system blocking agents, the investigators of the PREDIAN (Pentoxifylline for Renoprotection in Diabetic Nephropathy) trial reported it delayed the eGFR loss in stage 3–4 kidney disease in diabetic patients." (PMID 31547288, 2019). "Although glycemic control along with blood pressure control and blockade of renin–angiotensin–aldosterone system represents a cornerstone of the prevention of new-onset diabetic nephropathy, 30% of diabetic patients will develop significant renal insufficiency." (PMID 31757028, 2019). "However, the researches regarding the direct effect of H2S on renin activity and release in diabetic kidney disease are still rare." (PMID 31390847, 2019). "We will utilise this assay for the measurement of urinary cell levels of mRNAs for proteins implicated in diabetic nephropathy (e.g. TGF-β1), mRNAs that may be regulated by vitamin D (e.g. renin) and podocyte-associated mRNAs (e.g. podocin)." (PMID 29665833, 2018). "This was observed despite there being no functional differences in albumin excretion between the intervention (renin–angiotensin system blockade) and placebo groups, thus highlighting the relevance of the retinal microvasculature as an early biomarker of diabetic nephropathy." (PMID 29396691, 2018). "Inhibitors of the renin-angiotensin-aldosterone system (RAAS) have been shown to be not only cardio protective but in addition exhibit particular nephro protective effects in patients with diabetic kidney disease." (PMID 28926607, 2017). "Some studies have suggested that dual blockage of renin–angiotensin system may provide additive benefit in diabetic nephropathy, but further studies are needed to validate such therapy, which should be used with caution." (PMID 27039185, 2016). "Renin-angiotensin system (RAS) plays a key role in the pathogenesis of diabetic nephropathy." (PMID 25918729, 2015). "RAAS is known to play a major role in diabetic nephropathy, and vitamin D suppresses renin release." (PMID 26109389, 2015). "The combination of metformin, silymarin and renin-angiotensin system inhibitors or angiotensin receptor blockers may have additive kidney protective property to prevent or slowing the progression of diabetic nephropathy." (PMID 25340091, 2012). "The development of diabetic nephropathy is influenced by hyperglycemia, which can trigger various mechanisms such as increased oxidative stress, advanced glycation end products production, and activation of renin-angiotensin system and protein kinase C pathways." (PMID 37513920, 2023). "Moreover, in diabetic nephropathy in mice, hyperglycemia induces renin release through SUCNR1." (PMID 34572472, 2021).